IPO4 (importin 4)
Description:
Nuclear transport receptor that mediates nuclear import of proteins, such as histones, RPS3A, TNP2 and VDR. Serves as receptor for nuclear localization signals (NLS) in cargo substrates. Is thought to mediate docking of the importin/substrate complex to the nuclear pore complex (NPC) through binding to nucleoporin and the complex is subsequently translocated through the pore by an energy requiring, Ran-dependent mechanism. At the nucleoplasmic side of the NPC, Ran binds to the importin, the importin/substrate complex dissociates and importin is re-exported from the nucleus to the cytoplasm where GTP hydrolysis releases Ran. The directionality of nuclear import is thought to be conferred by an asymmetric distribution of the GTP- and GDP-bound forms of Ran between the cytoplasm and nucleus. Mediates the nuclear import of the histone H3-H4 dimer when in complex with ASF1 (ASF1A or ASF1B). Also mediates the nuclear import of monomeric histones H3.1 and H4. Mediates the ligand-independent nuclear import of vitamin D receptor (VDR). In vitro, mediates the nuclear import of human cytomegalovirus UL84 by recognizing a non-classical NLS.
Synonyms: Imp4; FLJ23338
Tractability: Small molecule: a structure with a bound ligand is known. PROTAC: ubiquitination databases record sites on it; its protein half-life has been measured.
Gene: Protein-coding gene on chromosome 14 (24,180,219 to 24,188,990, reverse strand). Ensembl gene ENSG00000196497.
Subcellular location: Cytoplasm; Nucleus
Subcellular location (Human Protein Atlas): Cytosol
Gene Ontology:
Molecular function: nuclear import signal receptor activity; nucleocytoplasmic carrier activity; protein binding; small GTPase binding
Biological process: protein import into nucleus; protein localization to nucleus; intracellular protein transport
Cellular component: chromatin; cytoplasm; membrane; nucleus; protein-containing complex
Genetic constraint (gnomAD): Loss-of-function variants: 91 observed, 134.92 expected, observed/expected ratio (o/e) 0.67, 90% interval 0.57 to 0.8. The upper end of that interval is the gene's LOEUF score, 0.8, which puts it in group 3 of 6, group 1 being the genes least tolerant of losing a copy. Missense variants: 1,279 observed, 1,424.2 expected, observed/expected ratio (o/e) 0.9, 90% interval 0.86 to 0.94. Synonymous variants: 607 observed, 604.38 expected, observed/expected ratio (o/e) 1, 90% interval 0.94 to 1.07.
Homologues: Orthologues: chimpanzee IPO4 (99% identical), macaque IPO4 (98% identical), pig IPO4 (91% identical), rabbit IPO4 (91% identical), guinea pig IPO4 (89% identical), dog IPO4 (87% identical), rat Ipo4 (84% identical), mouse Ipo4 (82% identical), tropical clawed frog ipo4 (48% identical), zebrafish ipo4 (47% identical), Drosophila melanogaster Apl (28% identical), Drosophila melanogaster Arts (28% identical). Paralogues in human: IPO5 (21% identical), RANBP6 (21% identical), TNPO2 (16% identical), TNPO1 (16% identical), KPNB1 (15% identical).
Diseases named in the same sentence as IPO4 in open-access papers:
IPO4 is named in the same sentence as 10 diseases in open-access papers, as found by Europe PMC text mining. Sharing a sentence is not in itself a finding about the gene and the disease. The quoted sentences say what the papers report.
gastric cancer (2 papers, 2021 to 2024). A primary or metastatic malignant neoplasm involving the stomach. "IPO4 is a histone transport protein that is usually highly expressed in gastric cancer tissues, and inhibiting IPO4 can weaken the proliferation and migration ability of gastric cancer cells." (PMID 39726754, 2024).
glioma (1 paper, 2024). A benign or malignant brain and spinal cord tumor that arises from glial cells (astrocytes, oligodendrocytes, ependymal cells). "Following the outcomes of functional experiments, we verify that IPO4 promotes proliferation, EMT, migration, and invasion of glioma cells, suggesting that IPO4 may serve as a novel underlying therapeutic target for glioma." (PMID 38734657, 2024). "Finally, the gene IPO4 with the highest risk coefficient was selected from the risk model, and its role in glioma progression was further verified by real-time quantitative PCR (RT-qPCR), Western Blot analysis and cell function experiments in glioma cell lines." (PMID 38734657, 2024). "Subsequent functional experiments revealed that knocking down IPO4 reduced the proliferation, migration, and invasion of glioma cells, indicating IPO4 as a potential innovative target for glioma therapeutic interventions." (PMID 38734657, 2024). "Finally, the effect of Importin-4(IPO4) on glioma has been further confirmed through RT-qPCR, Western blot, and cell functional experiments." (PMID 38734657, 2024).
ovarian carcinoma (1 paper, 2025). A malignant neoplasm originating from the surface ovarian epithelium. "The tumor suppressor RNF180 and its downstream target IPO4 have been validated in ovarian cancer models, forming a crucial molecular regulatory network." (PMID 41154754, 2025).
vitamin D deficiency (1 paper, 2024). A nutritional condition produced by a deficiency of VITAMIN D in the diet, insufficient production of vitamin D in the skin, inadequate absorption of vitamin D from the diet, or abnormal conversion of vitamin D to its bioactive metabolites. "IPO4 encodes importin 4 and its reduced expression is implicated with necrosis and Vitamin D deficiency in chronic liver disease." (PMID 38992651, 2024).
tumor (6 papers, 2013 to 2025). "Here, we further demonstrated that FOXM1D, acting as an adhesive protein, continues to interact with multiple proteins such as PKM2, the NF‐κB subunits of p65 and p50, importin 4, and VPS11, and thus promotes tumor glycolysis and angiogenesis." (PMID 33314660, 2021). "The upregulations of S100A4, MARCKSL1, BCAM, BAG4, IPO4 and CPSF7 in pHAGE-ELL(C595A) tumours were confirmed." (PMID 27009366, 2016).
cancer (3 papers, 2020 to 2023). A tumor composed of atypical neoplastic, often pleomorphic cells that invade other tissues. "Ipo4 is thought to be a key gene contributing to the progression and development of gastric and other cancers." (PMID 37398910, 2023). "This also highlights ipo4 as a gene target for cancer drug therapy." (PMID 37398910, 2023). "IPO4, as an importin-β family protein, has rarely been reported in cancers and chemoresistance." (PMID 32661323, 2020).
IPO4 also shares sentences with these, for which no sentence is quoted: adenocarcinomas of the lung (1 paper); cervical cancer (1); lung carcinoma (1); neuroblastoma (1).